METTL16 (methyltransferase 16, RNA N6-adenosine)
Description:
RNA N6-methyltransferase that methylates adenosine residues at the N(6) position of a subset of RNAs and is involved in S-adenosyl-L-methionine homeostasis by regulating expression of MAT2A transcripts. Able to N6-methylate a subset of mRNAs and U6 small nuclear RNAs (U6 snRNAs). In contrast to the METTL3-METTL14 heterodimer, only able to methylate a limited number of RNAs: requires both a 5'UACAGAGAA-3' nonamer sequence and a specific RNA structure. Plays a key role in S-adenosyl-L-methionine homeostasis by mediating N6-methylation of MAT2A mRNAs, altering splicing of MAT2A transcripts: in presence of S-adenosyl-L-methionine, binds the 3'-UTR region of MAT2A mRNA and specifically N6-methylates the first hairpin of MAT2A mRNA, preventing recognition of their 3'-splice site by U2AF1/U2AF35, thereby inhibiting splicing and protein production of S-adenosylmethionine synthase. In S-adenosyl-L-methionine-limiting conditions, binds the 3'-UTR region of MAT2A mRNA but stalls due to the lack of a methyl donor, preventing N6-methylation and promoting expression of MAT2A. In addition to mRNAs, also able to mediate N6-methylation of U6 small nuclear RNA (U6 snRNA): specifically N6-methylates adenine in position 43 of U6 snRNAs. Also able to bind various lncRNAs, such as 7SK snRNA (7SK RNA) or 7SL RNA. Specifically binds the 3'-end of the MALAT1 long non-coding RNA.
Synonyms: METT10D; MGC3329
Tractability: Small molecule: a structure with a bound ligand is known; it has a high-quality binding pocket. PROTAC: ubiquitination databases record sites on it; its protein half-life has been measured.
Target class: Enzyme; Transferase
Gene: Protein-coding gene on chromosome 17 (2,405,562 to 2,511,891, reverse strand). Ensembl gene ENSG00000127804.
Subcellular location: Nucleus; Cytoplasm
Subcellular location (Human Protein Atlas): Nucleoplasm; Cytosol
Gene Ontology:
Molecular function: mRNA m(6)A methyltransferase activity; RNA binding; RNA stem-loop binding; U6 snRNA (adenine-(43)-N(6))-methyltransferase activity; U6 snRNA 3'-end binding; 23S rRNA (adenine(1618)-N(6))-methyltransferase activity; methyltransferase activity
Biological process: mRNA processing; negative regulation of 3'-UTR-mediated mRNA stabilization; post-transcriptional regulation of gene expression; regulation of mRNA splicing, via spliceosome; S-adenosylmethionine biosynthetic process; snRNA (adenine-N6)-methylation; mRNA catabolic process; mRNA destabilization; rRNA base methylation; positive regulation of mRNA catabolic process; regulation of mRNA stability; RNA modification
Cellular component: cytoplasm; nucleoplasm; nucleus
Genetic constraint (gnomAD): Loss-of-function variants: 18 observed, 54.21 expected, observed/expected ratio (o/e) 0.33, 90% interval 0.23 to 0.49. The upper end of that interval is the gene's LOEUF score, 0.49, which puts it in group 2 of 6, group 1 being the genes least tolerant of losing a copy. Missense variants: 414 observed, 691.81 expected, observed/expected ratio (o/e) 0.6, 90% interval 0.55 to 0.65. Synonymous variants: 237 observed, 260.11 expected, observed/expected ratio (o/e) 0.91, 90% interval 0.82 to 1.01.
Homologues: Orthologues: chimpanzee METTL16 (98% identical), macaque METTL16 (97% identical), dog METTL16 (91% identical), pig METTL16 (91% identical), rabbit METTL16 (91% identical), guinea pig METTL16 (90% identical), mouse Mettl16 (88% identical), rat Mettl16 (88% identical), tropical clawed frog mettl16 (70% identical), zebrafish mettl16 (63% identical), Caenorhabditis elegans mett-10 (28% identical), Drosophila melanogaster CG7544 (23% identical).
Diseases named in the same sentence as METTL16 in open-access papers:
METTL16 is named in the same sentence as 80 diseases in open-access papers, as found by Europe PMC text mining. Sharing a sentence is not in itself a finding about the gene and the disease. The quoted sentences say what the papers report.
gastric cancer (25 papers, 2021 to 2026). A primary or metastatic malignant neoplasm involving the stomach. "High METTL16 expression is associated with poor prognosis in several cancers, including gastric cancer, hepatocellular carcinoma, esophageal cancer, colorectal cancer, lung cancer, glioblastoma, melanoma, osteosarcoma, breast cancer, cholangiocarcinoma, and leukemia." (PMID 41459114, 2026). "Furthermore, in gastric cancer, elevated copper levels were associated with METTL16‐mediated cuproptosis, where lactylation of METTL16 was identified as a key regulatory mechanism that enhances its function in m6A modification of FDX1 mRNA." (PMID 40919129, 2025). "In summary, METTL16 promotes GC cell proliferation and tumor progression through m6A-mediated stabilization of Cyclin D1 and modulation of cuproptosis and histone-associated signaling, highlighting its potential as a therapeutic target in gastric cancer." (PMID 41322419, 2025). "Furthermore, METTL16 was shown to be substantially expressed in gastric cancer and colorectal cancer cells, and was linked to a poor prognosis." (PMID 36091006, 2022). "Notably, accumulating evidence showed that METTL16 has been associated with a bad prognosis and has been found to be highly expressed in gastric cancer and colorectal cancer cells." (PMID 36091006, 2022). "In tumors such as hepatocellular carcinoma, gastric cancer, and breast cancer, high METTL16 expression is frequently correlated with enhanced tumor invasiveness, poor differentiation, and reduced overall survival." (PMID 41322419, 2025). "High copper content in gastric cancer tissues promotes lactylation of methyltransferase-like protein 16 (METTL16) and ultimately induces cuproptosis in GC cells by upregulating FDX1 protein levels." (PMID 40897695, 2025). "In gastric cancer, METTL16 K229la increases m6A modification of ferredoxin 1 mRNA, which triggers cuproptosis." (PMID 40994548, 2025). "METTL16 K229 upregulates ferredoxin 1 in gastric cancer, disrupting copper metabolism and inducing cuproptosis." (PMID 40994548, 2025). "The combination of the SIRT2 inhibitor AGK2 and elesclomol promotes cuproptosis in gastric cancer cells by enhancing the lactylation of METTL16 at lysine 229 and increasing FDX1 protein levels." (PMID 40897695, 2025). "In gastric cancer, the lactylation of METTL16 promotes cuproptosis through m6A modification on FDX1 mRNA." (PMID 40276654, 2025). "Elevated expression of METTL16 has been shown in multiple malignancies, such as hepatocellular carcinoma, lung cancer and gastric cancer, which indicates that METTL16 is broadly important in cancer." (PMID 38084791, 2024). "For example, METTL16 promotes gastric cancer proliferation through induction of cyclinD1 expression." (PMID 38084791, 2024). "In gastric cancer, researchers found that METTL16 is highly expressed in cancer tissues, and METTL16-mediated m6A methylation promotes GC cell proliferation by enhancing cyclin D1 expression." (PMID 37182151, 2023). "A recent study has shown that METTL16 promotes gastric cancer proliferation by up-regulating cyclin D1 expression." (PMID 37340443, 2023). "Although the oncogenic roles of METTL16 in gastric cancer has been reported, the role, expression, and clinical relevance of METTL16 in other cancers, including HCC, are still unclear." (PMID 35596159, 2022). "METTL16 was expressed in both cytoplasm and nucleus of cancer cells, and the expression level of METTL16 in gastric cancer cells was much higher than that in surrounding non‐cancer cells." (PMID 34075693, 2021). "In gastric cancer, for example, inhibition of METTL16 may sensitize tumor cells to copper ionophores, amplifying cuproptosis." (PMID 41459114, 2026). "In gastric cancer, METTL16 K229la status is directly correlated with its enzymatic activity." (PMID 40994548, 2025). "METTL16 has recently been confirmed to promote the development of gastric cancer by cyclin D139." (PMID 37859814, 2023).
gastric cancer (continued). "While METTL16 was initially recognized as an essential factor for mouse embryonic development by regulating Mat2a mRNA expression, subsequent evidence has shown the involvement of METTL16 in the progression of several cancers, including gastric cancer, hepatocellular carcinoma, and breast cancer." (PMID 37817227, 2023). "Moreover, METTL16-mediated m6A methylation boosted gastric cancer cell proliferation by increasing cyclin D1 expression." (PMID 36091006, 2022). "The fact that the same gene encoding the methyltransferase has different functions in various malignancies could explain the difference in METTL16’s prognostic efficacy between gastric cancer and liver cancer." (PMID 36091006, 2022). "Overexpression of METTL16 could promote the proliferation of gastric cancer cells and colony formation." (PMID 34075693, 2021). "In gastric cancer, METTL3 interacts with poly(A) binding protein cytoplasmic 1 (PABPC1) and stabilizes its association with the cap-binding complex eukaryotic translation initiation factor 4F (eIF4F), whereas METTL16 directly interacts with the translation repressor eIF4E2 in lung cancer." (PMID 41459114, 2026). "Emerging research proved METTL16-mediated m6A modification on FDX1 mRNA was critical for cuproptosis in gastric cancer (GC), and METTL16 lactylation significantly promoted the therapeutic efficacy of the copper ionophore-elesclomol." (PMID 39329964, 2024). "METTL16 enhances the stability of CCND1 mRNA through methylation modification, thereby increasing CCND1 expression and promoting the proliferation of gastric cancer cells." (PMID 41194259, 2025). "Specifically, lactylation of methyltransferase-like protein 16 (METTL16) at lysine 229 induces m6A modification of ferredoxin 1 (FDX1) mRNA, leading to elevated FDX1 expression and enhanced cuproptosis in gastric cancer cells." (PMID 41152975, 2025). "However, as a key m6A methyltransferase, METTL16 has not been thoroughly studied in gastric cancer (GC)." (PMID 34075693, 2021).
breast carcinoma (24 papers, 2020 to 2026). "In breast cancer, METTL16 expression is closely linked to recurrence-free survival, highlighting its potential as a biomarker for predicting treatment efficacy." (PMID 41459114, 2026). "Recent studies have revealed that RNA m6A modification contributes to breast cancer development, with the novel m6A methyltransferase METTL16 implicated in regulating key gene expression and signaling pathways, thereby affecting tumor cell proliferation, metastasis, and therapeutic sensitivity." (PMID 41322419, 2025). "However, the high expression of METTL16 has been linked with poor clinicopathological features and survival outcomes in breast cancer patients." (PMID 40015977, 2025). "Moreover, METTL16 is also implicated in the growth and metastasis of breast cancer." (PMID 39972939, 2025). "In breast cancer, the up-regulation of METTL16 expression leads to increased m6A modification of GPX4 mRNA, enhancing the expression of GPX4." (PMID 41459114, 2026). "This METTL16-mediated regulation helps breast cancer cells evade ferroptosis, promoting cancer growth and development." (PMID 41459114, 2026). "The overexpression of METTL16 exhibits a positive correlation with the growth and metastasis of breast cancer cells." (PMID 39972939, 2025). "In breast cancer, METTL16 is highly expressed in tumor tissues and cells, and its inhibition markedly suppresses BC cell proliferation, migration, and invasion." (PMID 41322419, 2025). "In breast cancer, METTL16 epigenetically upregulates GPX4 through m6A modification, thereby inhibiting ferroptosis and promoting cancer progression." (PMID 39248438, 2024). "The downregulation of METTL16 decreased m6A methylation, suppressed the tumorigenic potential of breast cancer cells, induced ferroptosis, and enhanced the degradation of glutathione peroxidase 4 (GPX4) RNA in breast cancer cells." (PMID 36835633, 2023). "While in other cases, there also have been reported that METTL16 is underexpressed in endometrial cancer, urothelial carcinoma, pancreatic ductal adenocarcinoma, and breast cancer." (PMID 38045858, 2023). "We also examined METTL16’s localization in a series of MCF10 breast cancer cells representing different stages of breast cancer progression." (PMID 31940410, 2020). "Breast Cancer Gene-Expression Miner v4.5 showed that LRPPRC level was negatively associated with ER and PR expression, while METTL16, RBM15B, ZC3H13 level was positively linked with ER and PR expression." (PMID 33362863, 2020). "The high expression of YTHDF3, ZC3H13, LRPPRC, and METTL16 indicated poor survival rate in patients with breast cancer, while high expression of RBM15B pointed to a better survival rate." (PMID 33362863, 2020). "According to the clinical database of breast cancer of TCGA, RBM15B, YTHDF3, ZC3H13, METTL16, and LRPPRC were picked up indicating strong associations with clinical characteristics." (PMID 33362863, 2020). "From another perspective, Kaplan-Meier Plotter platform showed that the relatively high expression of YTHDF3 and LRPPRC and the relatively low expression of RBM15B, ZC3H13, and METTL16 in breast cancer patients had worse Relapse-Free Survival (RFS)." (PMID 33362863, 2020). "In breast cancer, METTL16 expression correlates with estrogen receptor (ER) and progesterone receptor (PR) levels, indicating that it may play different roles in various breast cancer subtypes." (PMID 41459114, 2026). "In addition, METTL16 suppression attenuates breast cancer progression by inhibiting tumor growth and metastatic dissemination." (PMID 40986143, 2025). "In summary, METTL16 promotes breast cancer progression by regulating FBXO5-mediated proliferation and EMT as well as GPX4-mediated ferroptosis resistance, and targeting METTL16 via advanced nanoparticle-based delivery represents a promising therapeutic strategy for TNBC." (PMID 41322419, 2025).
breast carcinoma (continued). "The results in breast cancer patients showed that the relatively high expression of YTHDF3 and LRPPRC were remarkably associated with worse RFS, whereas relatively high expression of RBM15B, ZC3H13, and METTL16 had better RFS." (PMID 33362863, 2020). "We also found that the poor OS was related to the overexpression level of the METTL16 gene in CRC and breast cancer." (PMID 40015977, 2025). "Mechanistically, METTL16 knockdown decreased intracellular GSH levels and increased MDA, Fe2+ and LPO levels, similar to the findings in breast cancer." (PMID 39744432, 2025). "Conversely, FBXO5 overexpression can rescue the tumor-suppressive effects of METTL16 knockdown, confirming the critical role of the METTL16–FBXO5 axis in breast cancer progression." (PMID 41322419, 2025). "Among them, the expression of RBM15, VIRMA, HNRNPA2B1, and YTHDF1/2/3 were significantly upregulated, but METTL3, METTL14, METTL16, WTAP, FTO, YTHDC1, and EIF3A had lower expression in breast cancer compared to normal samples." (PMID 34804948, 2021). "In HER-2 (+) breast cancer patients, LRPPRC, METTL16, RBM15B, and ZC3H13 expressed lower than the HER-2 (−)." (PMID 33362863, 2020). "METTL3, METTL16, ZC3H13, YTHDC1 and FTO were expressed at a low level in breast cancer, while KIAA1429, RBM15, and YTHDF1 were expressed at a high level." (PMID 33362863, 2020). "In HER-2 (+) breast cancer patients, the expression of LRPPRC, METTL16, RBM15B, and ZC3H13 were all lower than the HER-2 (−) group." (PMID 33362863, 2020). "Mechanistically, METTL16-mediated m6A modification enhances FBXO5 mRNA stability through a post-transcriptional regulatory mechanism, thereby driving its oncogenic functions and facilitating malignant progression in breast cancer." (PMID 40986143, 2025). "In breast cancer (BRCA), the model selected HNRNPC, IGF2BP2, IGF2BP3, FTO, METTL16, and ALKBH1." (PMID 40565233, 2025). "METTL16 reduced the m6A methylation level of iron-dead GPX4 mRNA and significantly promoted the degradation of GPX4 mRNA, suggesting that METTL16 enhances the expression level of GPX4 through m6A modification, and thus inhibits iron-death to promote the proliferation of breast cancer cells." (PMID 39289775, 2024). "Furthermore, METTL16 enhanced GPX4 expression in a m6A-dependent manner, thus promoting the malignant progression of breast cancer via inhibiting ferroptosis." (PMID 38065948, 2023). "METTL16, an m6A methyltransferase discovered recently, operates independently from the METTL3/14 complex and holds significance in a range of cancers, including hepatocellular carcinoma, pancreatic ductal adenocarcinoma, epithelial ovarian cancer, breast cancer, and cholangiocarcinoma." (PMID 40095756, 2025). "Additionally, bioinformatics analyses have shown that METTL16 is overexpressed in esophageal cancer, colorectal cancer (CRC), and predicts poor survival in HCC, CRC, endocrine system tumors, glioma, melanoma, soft-tissue sarcomas, and breast cancer." (PMID 38045858, 2023).